VCPKMT (valosin containing protein lysine methyltransferase)
Description:
Protein N-lysine methyltransferase that specifically trimethylates 'Lys-315' of VCP/p97; this modification may decrease VCP ATPase activity.
Synonyms: VCP-KMT; C14orf138; METTL21D
Tractability: Small molecule: a structure with a bound ligand is known; a high-quality ligand is known. PROTAC: ubiquitination databases record sites on it.
Target class: Writer; Protein methyltransferase; Epigenetic regulator
Gene: Protein-coding gene on chromosome 14 (50,108,632 to 50,116,600, reverse strand). Ensembl gene ENSG00000100483.
Subcellular location: Cytoplasm
Subcellular location (Human Protein Atlas): Cytosol
Pathways (Reactome):
Metabolism of proteins: Protein methylation
Gene Ontology:
Molecular function: ATPase binding; protein binding; protein-lysine N-methyltransferase activity; protein methyltransferase activity
Biological process: peptidyl-lysine trimethylation; ERAD pathway; negative regulation of ATP-dependent activity
Cellular component: cytoplasm; cytosol; intracellular protein-containing complex; protein-containing complex
Genetic constraint (gnomAD): Loss-of-function variants: 23 observed, 19.43 expected, observed/expected ratio (o/e) 1.18, 90% interval 0.85 to 1.66. The upper end of that interval is the gene's LOEUF score, 1.66, which puts it in group 6 of 6, group 1 being the genes least tolerant of losing a copy. Missense variants: 279 observed, 221.99 expected, observed/expected ratio (o/e) 1.26, 90% interval 1.14 to 1.39. Synonymous variants: 118 observed, 93.72 expected, observed/expected ratio (o/e) 1.26, 90% interval 1.08 to 1.47.
Homologues: Orthologues: chimpanzee VCPKMT (99% identical), macaque VCPKMT (96% identical), dog VCPKMT (94% identical), rabbit VCPKMT (94% identical), pig VCPKMT (92% identical), guinea pig VCPKMT (92% identical), mouse Vcpkmt (90% identical), rat Vcpkmt (87% identical), tropical clawed frog vcpkmt (63% identical), zebrafish vcpkmt (59% identical), Caenorhabditis elegans vkmt-1 (30% identical). Paralogues in human: METTL21A (31% identical), EEF1AKMT3 (29% identical), METTL21EP (28% identical), METTL21C (24% identical), METTL23 (19% identical).
Diseases named in the same sentence as VCPKMT in open-access papers:
VCPKMT is named in the same sentence as 2 diseases in open-access papers, as found by Europe PMC text mining. Sharing a sentence is not in itself a finding about the gene and the disease. The quoted sentences say what the papers report.
cancer (3 papers, 2015 to 2023). A tumor composed of atypical neoplastic, often pleomorphic cells that invade other tissues. "Recently, it has been shown that VCPKMT is involved in cancer metastasis formation." (PMID 26544960, 2015).
tumor (1 paper, 2023). "Another work described three other tumor genes (CCDC66, ZRANB2 and VCPKMT) for positive margin prediction based on gene expression signature." (PMID 38188288, 2023).